IFNB1 (interferon beta 1)
Diseases named in the same sentence as IFNB1 in open-access papers (continued):
Sharing a sentence is not in itself a finding about the gene and the disease.
co-infection (24 papers, 2008 to 2026). "Along these lines, we found in our study that CCL2 was significantly reduced in the plasma of IAV-infected mice and that both monocausal bacterial infection and co-infection featured Ifnb1 overexpression in the lung." (PMID 36365071, 2022). "While Ifnb1 was only upregulated following GAS infection, Tgfb1 was downregulated after GAS infection as well as co-infection." (PMID 36365071, 2022). "We observed a significant upregulation of type I and III IFN (i.e., IFNB1 and IFNL1, respectively) expression at early times following IAV DIP and SARS-CoV-2 co-infection compared with SARS-CoV-2 single infection." (PMID 34359926, 2021). "To precisely define the effects of cellular co-infection on IFN induction, we measured the effects of varying bulk MOI on the induction of both type I (IFNB1) and type III (IFNL1) IFN transcription in both MDCK and A549 cells at 8 and 18 hpi under single cycle infection conditions." (PMID 33064776, 2020). "Finally,the mRNA levels of several cytokines were determined, and showed that the transcription of IFNB1, TNF, IL1B, and OASL was higher in the co-infection group than in the singly infected group, which may have been the consequence of increased PEDV replication." (PMID 37065133, 2023).
dengue (21 papers, 2007 to 2023). "Other studies have indicated that PCSK9 inhibits IFNB1 expression, and contributes to dampened antiviral cellular responses in Dengue fever patients, which could be abrogated by a PCSK9 inhibitor." (PMID 35224060, 2022). "In addition, monocytes of individuals with past severe dengue (SD) exhibited a significant upregulation of IFNB-1, RIG-I, and NLRP3 genes compared to those with past non-SD that was accompanied with higher viral loads, suggesting that initial innate immune responses may influence disease outcome." (PMID 32455136, 2020).
colorectal cancer (20 papers, 1999 to 2025). A primary or metastatic malignant neoplasm that affects the colon or rectum. "We report here that the PDCD1 transcription level exhibits a positive correlation with the IFNB1 and IFNAR1 level in myeloid cells in human colorectal cancer patients." (PMID 38995014, 2024). "We determined that the expression level of PDCD1 is positively correlated with the levels of IFNB1 and IFNAR1 in myeloid cells in human colorectal cancer." (PMID 38995014, 2024). "We report that the expression level of PDCD1, the gene that encodes the PD-1 protein, is positively correlated with the levels of IFNB1 and IFNAR1 in myeloid cells in human colorectal cancer." (PMID 38995014, 2024).
myocarditis (20 papers, 2011 to 2025). Myocarditis is a condition that is characterized by inflammation of the heart muscle (myocardium). "In CVB3 infection, the expression of interferon beta (IFN-β, gene IFNB1), tumor necrosis factor alpha (TNF-α, gene TNF), interleukin-1 beta (IL-1β, gene IL1B) and interleukin-8 (IL-8, gene CXCL8) are highly upregulated and correlate with myocarditis severity." (PMID 41156753, 2025).
pancreatic cancer (20 papers, 2005 to 2025). "Notably, the MEK1/2 inhibitor Trametinib was shown to be able to induce retroelement activation and IFNB1 gene expression in pancreatic cancer cells." (PMID 38724853, 2024).
Listeria infection (19 papers, 2009 to 2025). "In contrast, 3-day Listeria infection, triggered the expression of IFNL1 (coding IFN-λ1) and, to a lesser extent, IFNB1 (coding IFN-β) and IFNL2 (coding IFN-λ2) transcripts in HepG2 cells, while low levels of IFNB1 transcripts were detected in infected PMH." (PMID 34858876, 2021).
colitis (18 papers, 2007 to 2026). Inflammation of the colon. "Q-PCR analysis showed that DSS-colitis-induced up-regulated mRNA expression of Cgas, Il10, Ifnb1, Tnf, and Il1b was significantly reduced in STING deficient mice (For Cgas: p < 0.01; For Il10: p < 0.01; For Ifnb1: p < 0.001; For Tnf: p < 0.001; For Il1b: p < 0.001)." (PMID 36467059, 2022). "The results showed that the mRNA expression levels of Cgas, Il10, Cxcl10, Ifnb1, Tnf, Il6, and Il1b exhibited no obvious difference between GCV and vehicle treatment groups in DSS-colitis in STINGgt/gt mice (all p > 0.05)." (PMID 36467059, 2022).
prostate carcinoma (17 papers, 2007 to 2025). A carcinoma that arises from epithelial cells of the prostate gland. "IFNB1 itself and IRF3 encoding a key transcription factor for its synthesis appeared downregulated in the group of prostate cancers with both alterations, too." (PMID 17280610, 2007).
colon carcinoma (16 papers, 2018 to 2025). "We also observed that the PD-1 expression level is also positively correlated with the expression levels of IFNB1 and IFNAR1 in the myeloid cells of human colon cancer patients." (PMID 38995014, 2024). "In MakA-treated CT26 colon cancer cells, most cytokines stayed undetectable except for marginally induced Il6 and Ifnb1, neither of which was significantly altered in vivo." (PMID 41326332, 2025). "In contrast to IFNB1, IFNA expression is too weak to be detected in human colon carcinoma." (PMID 38995014, 2024).
gastric cancer (15 papers, 2012 to 2025). A primary or metastatic malignant neoplasm involving the stomach. "A recent investigation has revealed that the expression of five genes linked to the cGAS-STING pathway, namely IFNB1, IFNA4, IL6, NFKB2, and TRIM25, exhibits potential as a valuable prognostic marker for OS in patients suffering from gastric cancer." (PMID 38240703, 2024). "Conversely, TRIM6 depletion in mouse (MTC) and human (MKN28) gastric cancer cells resulted in a significant increase in the mRNA levels of IFNB1 and its downstream genes CXCL10 and ISG15 (or Ccl5) under HT-DNA treatment, and these effects were abolished by simultaneous cGAS knockout." (PMID 40817248, 2025).
tuberculosis (15 papers, 2017 to 2026). A chronic, recurrent infection caused by the bacterium Mycobacterium tuberculosis. "Our analyses of these data indicate that IMs were also the dominant IFNB1-expressing cells in non-human primates with active tuberculosis, and IMs did not express IFNB1 in naïve or latently infected lungs." (PMID 38029747, 2023).
sarcoma (10 papers, 2015 to 2025). A usually aggressive malignant neoplasm of the soft tissue or bone. "Because Atrx-deleted sarcoma cells had increased micronuclei after irradiation, we next tested whether Atrx deletion increased IFN-β (Ifnb1) expression after ionizing radiation in vitro." (PMID 37200088, 2023). "By searching TIMER web tool, we also found that the IFNB1 mRNA expression level was positively correlated with the infiltration levels CD8+ T cells, CD4+ T cells, and CD4+ Th2 cells in sarcoma." (PMID 35662245, 2022). "We also stimulated the 143B isogenic cell lines with cGAMP and found that the 143B ATRX KO cell line had significantly less expression of IFNB1, suggesting that at least part of the CGAS/STING pathway impairment was occurring downstream of CGAS in our human sarcoma cell lines." (PMID 37200088, 2023). "To test whether these findings also held true in human sarcomas, we used our isogenic 143B human sarcoma cell line with or without CRISPR ATRX knockout and assessed IFNB1 expression levels after treatment with oHSV-60, a 60-bp DNA sequence known to potently stimulate the CGAS/STING pathway." (PMID 37200088, 2023).
mesothelioma (9 papers, 2013 to 2023). A usually malignant and aggressive neoplasm of the mesothelium which is often associated with exposure to asbestos. "The IFNB1 gene is co-deleted in 70% of mesothelioma with CDKN2A deletion." (PMID 37296931, 2023). "However, for therapies inducing type-I IFN signaling, if the contribution of the production of IFNB1 by tumor cells themselves has a role, it should not be forgotten that some forms of mesothelioma have lost type-I IFN genes." (PMID 37296931, 2023).
lung adenocarcinoma (8 papers, 2012 to 2024). A carcinoma that arises from the lung and is characterized by the presence of malignant glandular epithelial cells. "Under the same physical dosage, it was investigated how various LET rays affected the upstream regulatory factors TREX1, IFNB1, important marker of immunogenic death, and PD-L1 in Lewis lung adenocarcinoma cells." (PMID 38495488, 2024).
breast tumor (7 papers, 2015 to 2025). "A possible relationship between type I IFNs and CD169-expression on Mo-M was supported by mRNA data from primary human breast tumors, where mRNA expression for the gene SIGLEC1 encoding CD169 significantly correlated with IFNA4 (P=6.25e-04) and IFNB1 (P=5.53e-41)." (PMID 37404831, 2023).
H1N1 virus infection (6 papers, 2017 to 2024). "The H7N9, H7N7 and H5N1 infected mouse lung transcriptome also showed higher levels of CXCL13, IL-6, IFNG, IFNB1, IRF9, IRF1, and TNF compared with 2009 pandemic H1N1 virus infections." (PMID 28558796, 2017).
triple-negative breast carcinoma (6 papers, 2016 to 2024). An invasive breast carcinoma which is negative for expression of estrogen receptor (ER), progesterone receptor (PR), and human epidermal growth factor receptor 2 (HER2).
bacterial pneumonia (5 papers, 2010 to 2022). Acute infection of the lung parenchyma caused by bacteria (e.g., Streptococcus pneumoniae, Haemophilus influenzae, Chlamydia pneumoniae, Mycoplasma pneumoniae, and Legionella pneumophila). "Because IFN-β can be produced by macrophages during Gram-negative pneumonia, we stimulated Reg1+/− or control BMDMs with heat-killed KP and assessed Ifnb1 mRNA." (PMID 35100872, 2022).
endometrial cancer (5 papers, 2013 to 2026). Primary or metastatic malignant neoplasm involving the endometrium (mucous membrane that lines the endometrial cavity). "Therefore, five endometrial cancer cell lines were treated with DMSO, 100nM, 200nM, and 500nM of AZD1775, and qRT-PCR was employed to measure the expression of CCL5, CXCL10, and IFNB1." (PMID 38169513, 2024).
E. coli infection (4 papers, 2012 to 2024). "The E. coli infection of IPEC-1 cells induced the upregulation of the IFNB1 gene encoding interferon beta 1 (logFC of 3.63) and the IFNGR1 gene (logFC of 3.55), encoding the ligand-binding alpha chain of the gamma interferon receptor." (PMID 32234079, 2020).
fungal infection (4 papers, 2014 to 2023). "Genes exclusively regulated by atRA during fungal infections included CXCL6 for A. fumigatus challenge, and the fungal pattern recognition receptor Dectin-2 (CLEC6A) as well as the type-I interferons IFNB1 and IFNA14 during C. albicans infection." (PMID 28094291, 2017).
leishmaniasis (4 papers, 2018 to 2022). Infectious disease that is transmitted through the bite of hematophagous female phlebotomine sand flies. "Furthermore, expression of IFNA1 and IFNB1 was highest in CD1c+ DCs relative to B cells (CD19+) and monocytes (CD14+), other likely cellular sources of these cytokines in experimental leishmaniasis." (PMID 32101732, 2020).
lymphoma (4 papers, 2016 to 2020). A malignant (clonal) proliferation of B- lymphocytes or T- lymphocytes which involves the lymph nodes, bone marrow and/or extranodal sites. "In addition, we observed co-expression of immune mediators, such as interferons and their targets (IFNA1-2, IFNA7-8, IFNB1, and IFNG), as well as proinflammatory cytokines (IL-1B and IL12B) and chemokines and their receptors (CXCL9-11 and CXCR3) by CpG(B)-STAT3dODN-treated lymphoma cells (right)." (PMID 29433938, 2018).
poliovirus infection (3 papers, 2013 to 2017). An disease or disorder caused by infection with Enterovirus C. "We found that siRNA for ZYX moderately reduced IFNB1 promoter activation after poliovirus infection." (PMID 28928438, 2017).
pulmonary TB (3 papers, 2013 to 2025). "(A) Representative 3D confocal images of paucibacillary (n=16) and multibacillary (n=16) pulmonary TB lesions of B6.Sst1S,Ifnb1 -YFP reporter mice stained with anti-4-HNE antibody (yellow)." (PMID 41037321, 2025).
bacteremia (2 papers, 2013 to 2023). "Ifnb1 mRNA in the lung was found to be upregulated before the onset of bacteremia, indicating its activation by the acute local immune response rather than secondary factors associated with bacteremia." (PMID 24244159, 2013). "Bacterial titers in the bloodstream were very low and close to the detection limit at 6 hours, indicating that upregulation of Ifnb1 mRNA reflected the acute local immune response, rather than secondary consequences of bacteremia." (PMID 24244159, 2013).
gastric tumor (2 papers, 2020 to 2025). "In this study, we investigated the gastric tumor response to radiation therapy, based on the Sting signal, IFNB1, TNFα, CXCL-9 as well as IL-10 gene expression, infiltration of DCs, Th and Teff cells in the tumor microenvironment, and PD-1/PD-L1 expression after radiation therapy." (PMID 32960261, 2020).
lupus erythematosus (2 papers, 2019 to 2024). An autoimmune, connective tissue chronic inflammatory disorder affecting the skin, joints, kidneys, lungs, heart, and the peripheral blood cells. "Discoid lupus erythematosus (DLE) was significantly separated from control skin by all of the signatures (p < .05); IFNB1 had the greatest size (Hedge’s g = 12.4) followed by IFNW1 (g = 9.7), IFNG (g = 8.7), IFNA2 (g = 7.9), IL12 (g = 5.2), and TNF (g = 2.8)." (PMID 31044165, 2019).
metastatic colorectal cancer (2 papers, 2020 to 2025). "In particular, patients with metastatic colorectal cancer carrying IFNB1 rs1051922 G/A and A/A allele showed a significantly shorter PFS than carriers of G/G allele." (PMID 41476984, 2025). "Variants in STING1 have been linked to cervical cancer development, while in patients with metastatic colorectal cancer treated with cetuximab-based first-line therapy, IFNB1 rs1051922 correlates with progression-free survival." (PMID 41476984, 2025).
oral cancer (2 papers, 2016 to 2018). "To determine whether the TAR RNA was able to directly induce expression of the same genes, we transfected TAR RNA into HSC3 and SCC9 oral cancer cells and found that TAR RNA significantly increased IFIT1, IFNB1, and DEFB103 expression in the cancer cells." (PMID 30389917, 2018).
bladder urothelial carcinoma (1 paper, 2025). "al., which contains CALR, IFNB1, and IFNG, showed a powerful function in bladder urothelial carcinoma prognosis and immune landscape determination." (PMID 40557150, 2025).
chorioamnionitis (1 paper, 2024). A morphologic finding indicating inflammation of the fetal sac membranes. "Membranes with chorioamnionitis display increased miR-223 and miR-338 expression, and miR-223 target genes (SPINK5, TGFB2, and IFNB1) are involved in the biological processes of negative regulation of immune and anti-inflammatory responses." (PMID 39574982, 2024).
Down syndrome (1 paper, 2021). "With the exception of IFNA1 expression, type I interferons (IFNA2 and IFNB1) were all upregulated, indicating that the axis IFNAR-STAT-OAS is upregulated in Down syndrome." (PMID 33479353, 2021).
fluorosis (1 paper, 2023). "The top 10 drugs have been reported in previous studies, namely Celastrol, LDN-193189, XPNPEP1, GNB5, Importazole, LDHB, NUAK1, IFNG, IFNB1, and YWHAH, suggesting that these drugs may be effective candidate drugs for the treatment of fluorosis." (PMID 36835629, 2023).
intrahepatic cholangiocarcinoma (1 paper, 2024). A carcinoma that arises from the intrahepatic bile duct epithelium in any site of the intrahepatic biliary tree. "Conversely, a modest increase in the expression of IFNA1, IFNB1, and IRF1 was observed in liver tissue sections from patients with intrahepatic cholangiocarcinoma." (PMID 38817870, 2024).
lymph node metastasis (1 paper, 2015). "Five genes (VEGFA, IFNB1, IGF1, TEK, and TGFBR1) are associated with angiogenesis, which provides clues to the mechanism of the association between epigenetic inactivation of CYB5R2 and lymph node metastasis." (PMID 26275421, 2015).
mucinosis (1 paper, 2025). "Drug-related mucinosis has been linked to interferon alfa-1, interferon beta-1, interleukin 12/23 inhibitors (ustekinumab), tumor necrosis factor-alfa inhibitors and interleukin 6 inhibitors (tocilizumab)." (PMID 40535966, 2025).
neurofibroma (1 paper, 2017). An intraneural or extraneural neoplasm arising from nerve tissues and neural sheaths. "Ifnb1 was also slightly down-regulated both in 1-month-old Nf1−/− SCs and 1-month-old Nf+/+ macrophages from Nf1fl/fl;DhhCre mice compared to their wild-type controls, suggesting that levels of IFN-β mRNA might be reduced even in early stages of neurofibroma growth." (PMID 28256556, 2017).
ovarian tumor (1 paper, 2022). "qRT-PCR analyses revealed that STINGPOX drives RSAD2 and IFNB1 expression in the ovarian tumor explants, consistent with our in vitro observations in cancer cell lines." (PMID 36713447, 2022).
overnutrition (1 paper, 2022). An imbalanced nutritional status resulting from excessive intake of nutrients. "The expression of Ifnb1 and its protein product IFN-β was also significantly higher in hepatocytes of HFD-fed mice treated with poly I:C, suggesting that hepatocytes are both targets and potential sources of IFN-Is in overnutrition." (PMID 35015731, 2022).
retinal detachment (1 paper, 2023). An eye emergency condition which may lead to blindness if left untreated. "VKH-like disease was previously reported with interferon alpha treatment but it was not the scenario with our patient who was treated with interferon beta 1-a for 3 months only and it was stopped completely 7 months before the development of the exudative retinal detachment." (PMID 36947273, 2023).
rosacea (1 paper, 2023). A chronic erythematous skin disorder that affects the face. "When comparing acute flare-ups with stabilized chronic lesions of rosacea in order to identify potentially unique patterns, we found a selective and significant increase in expression of type I IFNs IFNA2 and IFNB1 in flare-ups." (PMID 36633910, 2023).
ulcer (1 paper, 2021). "Transcriptional analysis of biopsy tissue indicated that type II interferon, IFNG, not type I (IFNA4 and IFNB1) nor type III (IFNL1, IFNL2, IFNL3) interferons, was the prevalent interferon gene detected in ulcer lesions and 8 weeks post-healed skin." (PMID 34552595, 2021).